NEAT1 (nuclear paraspeckle assembly transcript 1)
Diseases named in the same sentence as NEAT1 in open-access papers (continued):
Sharing a sentence is not in itself a finding about the gene and the disease.
osteoarthritis (9 papers, 2020 to 2025). A noninflammatory degenerative joint disease occurring chiefly in older persons, characterized by degeneration of the articular cartilage, hypertrophy of bone at the margins and changes in the synovial membrane. "Mechanistic studies reveal that ABPS mitigates chondrocyte endoplasmic reticulum stress via the lncRNA NEAT1/miR-377-3p regulatory axis, offering novel insights into osteoarthritis management." (PMID 41244813, 2025). "In conclusion, our study indicates that focusing on the piRNA hsa_piR_019949 and suppressing the expression of lncRNA NEAT1 holds promise as a therapeutic strategy for osteoarthritis." (PMID 38178210, 2024). "One group showed that lncRNA NEAT1 increased chondrocyte proliferation and reduced apoptosis via inhibition of miR-16–5p in osteoarthritis (Li." (PMID 37779916, 2023). "One example of previous studies was that the expression of NEAT1 and IL-8 was upregulated in the synoviocyte of osteoarthritis." (PMID 33193674, 2020). "We hypothesize that NEAT1 may serve as a downstream target gene regulated by hsa_piR_019949, potentially influencing chondrocyte metabolism and function in the context of osteoarthritis." (PMID 38178210, 2024). "Moreover, achyranthes bidentata polysaccharides (ABPS) increased the expression of lncRNA NEAT1 and decreased the miR-377–3p expression, leading to attenuation of endoplasmic reticulum in osteoarthritis." (PMID 37779916, 2023). "Interestingly, NEAT1 is also abundant in the rat model of osteoarthritis (OA) and contributes to the disease via different mechanisms that result in the increased production of inflammatory cytokines and the increased apoptosis of chondrocytes." (PMID 35127819, 2021). "And NEAT1 impeded the progression of osteoarthritis via the regulation of miR-181a-GPD1L axis." (PMID 32280304, 2020). "However, in osteoarthritis, NEAT1 and NLRP3 seem to have a relieving effect." (PMID 38178210, 2024). "LncRNA NEAT1 regulated cartilage matrix degradation via targeting miR-193a-3p and SOX5 pathways in osteoarthritis." (PMID 37779916, 2023). "Another group reported that lncRNA NEAT1 governed miR-543/PLA2G4A axis and led to inhibition of chondrocyte proliferation and induction of apoptosis in osteoarthritis." (PMID 37779916, 2023).
cholangiocarcinoma (8 papers, 2017 to 2022). A carcinoma that arises from the intrahepatic biliary tree (intrahepatic cholangiocarcinoma) or from the junction, or adjacent to the junction, of the right and left hepatic ducts (hilar cholangiocarcinoma). "For example, BAP1 conversely regulated the expression of NEAT-1, which contributed to sensitivity to gemcitabine in cholangiocarcinoma." (PMID 29654165, 2018). "Furthermore, short hairpin RNA (shRNA)-mediated silencing of NEAT1 significantly impaired cell proliferation, migration and invasion in cholangiocarcinoma." (PMID 30374364, 2018). "In breast invasive carcinoma (BRCA), cholangiocarcinoma (CHOL), and pheochromocytoma and paraganglioma (PCPG), NEAT1 expression was significantly decreased in tumors compared with normal tissues." (PMID 31186635, 2019). "A BAP1 dependent alteration in expression of lncRNA NEAT-1 was identified by RT-PCR based lncRNA expression profiling, and an inverse relationship between this lncRNA and BAP1 was observed in analysis of the Tumor Cancer Genome Atlas cholangiocarcinoma dataset." (PMID 28122578, 2017).
retinoblastoma (8 papers, 2011 to 2025). A malignant tumor that originates in the nuclear layer of the retina. "However, the role, expression status, and the detailed mechanism of NEAT1 in retinoblastoma (RB) yet need to be unraveled." (PMID 31038819, 2019). "Moreover, NEAT1 could regulate the proliferation, migration, and apoptosis of human retinoblastoma cells via regulation of the miR-204/CXCR4 axis." (PMID 32596382, 2020). "Interestingly, NEAT1, which is constitutively and highly expressed in normal tissues, with the exception of embryonic stem cells, was downregulated in lung, liver, esophageal and retinal cancers (retinoblastoma)." (PMID 21991387, 2011). "Previously reported that retinoblastoma invasion and proliferation can be inhibited by the miR-148b-3p/ROCK1 axis via the role of the lncRNA NEAT1." (PMID 40165339, 2025).
serous ovarian cancer (8 papers, 2010 to 2024). "It was reported that the RNA-binding protein (RBP) LIN28B bound to and stabilized NEAT1 in high-grade serous ovarian carcinoma (HGSOC)." (PMID 37986114, 2023). "In high-grade serous ovarian cancer, NEAT1 promotes cell proliferation and invasion in vitro and enhanced tumor growth in vivo." (PMID 32983133, 2020). "This study aimed to investigate the role of NEAT1 in HR function and whether targeting NEAT1 in serous ovarian cancer cells could increase PARPi sensitivity." (PMID 38356722, 2024). "That is, one group including: SSBP1, IFI6 DDT, IFI27, C11orf92, NFKBIA, TNXB, NEAT1 and TFG, was up-regulated in most patients with stage III serous ovarian cancer." (PMID 20969748, 2010).
triple-negative breast carcinoma (8 papers, 2015 to 2024). An invasive breast carcinoma which is negative for expression of estrogen receptor (ER), progesterone receptor (PR), and human epidermal growth factor receptor 2 (HER2). "In conclusion, the NQO1 expression in triple-negative breast cancer cells determined their radiosensitivity and was controlled by NEAT1." (PMID 32922184, 2020). "NEAT1 has garnered attention for its involvement in developing and progressing several cancer types, including CRC, gallbladder, breast, prostate, NSCLC, and triple-negative breast cancer." (PMID 38343745, 2024). "On the other hand, although the involvement of miRNAs is not clear, NEAT1 induces radioresistance in triple-negative breast cancer (TNBC) cells by upregulating the translation of NAD(P)H:quinone oxidoreductase rather than its transcription." (PMID 35054896, 2022). "To determine whether hypoxic induction of NEAT1 occurs more generally, we first surveyed a panel of estrogen receptor-positive (+) and -negative (−) and triple receptor negative breast cancer cell lines for hypoxia-dependent regulation of NEAT1." (PMID 25417700, 2015).
breast tumor (7 papers, 2016 to 2023). "Patients whose primary breast tumors showed a high expression of NEAT1, colon cancer associated transcript 2 (CCAT2), or metastasis associated lung adenocarcinoma transcript 1 (MALAT1) had shorter overall survival (OS)." (PMID 30545127, 2018). "Moreover, NEAT1 is frequently overexpressed in breast tumor samples compared to adjacent normal tissue and is associated with poor overall survival." (PMID 31992741, 2020). "This work establishes ALYREF as a potential prognostic factor in TNBC and demonstrates that ALYREF is important in breast tumor formation, at least in part, through the transcriptional and post-transcriptional regulation of the short NEAT1 isoform." (PMID 35776213, 2022). "Mutations were identified in the promoters of lncRNAs RMRP and nuclear paraspeckle assembly transcript 1 (NEAT1) that increased their expression in human breast tumors." (PMID 30545127, 2018). "The authors also found that NEAT1 increased the malignant biological behaviors of BRCA1- knockdown breast neoplasm cells through suppressing mir-129-5p and subsequently enhancing the expression of oncogene WNT4." (PMID 28118609, 2017). "These gain- and loss-of-function studies show that NEAT1 is functionally required for invasiveness, anchorage-independent growth and BCSC self-renewal of breast tumor cells and its overexpression leads to increased self-renewal of normal breast stem cells." (PMID 27556296, 2016). "Further, the authors identified a putative ceRNA network for NEAT1, as well as lncRNAs OPI5-AS1 and AC008124.1 in all breast tumors and each subtype." (PMID 30545127, 2018). "NEAT1 was also identified in a gene (ESR1, DKC1)–lncRNA (TERC and TUG1) interaction network in breast tumors from TCGA." (PMID 30545127, 2018). "Additionally, the level of lncRNAs NEAT1, CASC2, and LINC00299 in breast tumor tissues increased significantly by twofold, 1.5‐fold, and 2.3‐fold, respectively, compared to adjacent nonmalignant samples (p < 0.05)." (PMID 37706018, 2023).
Cognitive impairment (7 papers, 2020 to 2026). Abnormal cognition is characterized by deficits in thinking, reasoning, or remembering. "Therefore, in subsequent treatment, NEAT1 can promote the functional recovery of cognitive impairment caused by some diseases." (PMID 38543885, 2024). "Overall, these findings highlight NEAT1 as a potential therapeutic target for addressing both seizure activity and cognitive impairments in TSC." (PMID 41090516, 2026). "In the context of subarachnoid hemorrhage (SAH), a type of cerebral bleed leading to severe brain damage and often resulting in cognitive impairment, studies have found that nimodipine can ameliorate cognitive impairment post-SAH in rats via the lncRNA NEAT1/Mir-27a/MAPT axis." (PMID 38543885, 2024). "LncRNA nuclear enriched abundant transcript 1 (NEAT1) interacts with NEDD4L and promote PTEN-induced putative kinase 1 (PINK1)’s degradation, thereby the interaction between them is assumed to be responsible for mitochondria dysfunction and cognitive impairment." (PMID 38368488, 2024).
dengue (7 papers, 2019 to 2025). "While in dengue virus infection, the decreased level of NEAT1 correlates with the development of a severe dengue phenotype, in SARS-CoV-2 infection, NEAT1 has been associated with the cytokine storm." (PMID 38717150, 2024). "Nuclear Enriched Abundant Transcript 1 (NEAT1), which is a non-coding RNA, and the coding gene Interferon alpha-inducible protein 27 (IFI27) were highly co-expressed and negatively associated with the degree of dengue severity." (PMID 33330133, 2020). "This might explain NEAT1 as a differentiating bio-marker of severe dengue from dengue infection." (PMID 33330133, 2020).
heart failure (7 papers, 2018 to 2025). Inability of the heart to pump blood at an adequate rate to meet tissue metabolic requirements. "With regard to the underlying mechanism, our findings showed that Neat1 promoted the progression of cardiac fibrosis to heart failure by recruiting EZH2 to the promoter region of Smad7." (PMID 34980170, 2022). "Finally, in one study evaluating lncRNA NEAT1 as a biomarker for heart failure, serum lncRNA NEAT1 was diagnostic, and low circulating levels were able to predict overall survival." (PMID 38485860, 2024). "However, so far, the function and specific mechanisms of NEAT1 in cardiac fibrosis associated with heart failure remain largely unknown." (PMID 34980170, 2022). "Moreover, overexpressed NEAT1 is associated with heart failure." (PMID 34923910, 2022). "In heart failure, lncRNA NEAT1 was found to provide scaffolding between the enhancer of zeste homolog 2 (EZH2) and the Smad7 promotor region similar to lncRNA MALAT1, thereby decreasing the expression of Smad7 and leading to unbalanced TGFβ–driven fibrosis." (PMID 38485860, 2024). "In the present study, we have demonstrated that the lncRNA NEAT1 is upregulated in patients with heart failure." (PMID 34980170, 2022). "Our findings indicate that NEAT1/Neat1 was highly upregulated in the cardiac tissue of heart failure patients and mouse models of heart failure." (PMID 34980170, 2022). "NEAT1/Neat1 expression was found to be considerably high in patients with heart failure and mouse models of heart failure." (PMID 34980170, 2022). "A large amount of research indicates that long noncoding RNAs (lncRNAs) play an important role in cardiac fibrosis, but little is known about the specific function and mechanism of the lncRNA NEAT1 in the progression of cardiac fibrosis to heart failure." (PMID 34980170, 2022). "In summary, our results indicate that NEAT1 may be a novel target for the treatment of cardiac fibrosis and heart failure." (PMID 34980170, 2022). "In addition, both gain-of-function and loss-of-function experiments showed that Neat1 plays a role in promoting cardiac fibrosis, and this was confirmed through in vivo experiments on TAC mouse models of heart failure." (PMID 34980170, 2022). "Thus, targeted inhibition of Neat1 might be effective in slowing or halting the progression of cardiac fibrosis to heart failure." (PMID 34980170, 2022). "NEAT1 and MALAT1 were selected as vital regulators in heart failure induced by type 2 diabetes through bioinformatic analysis." (PMID 40282226, 2025). "In this study, we show for the first time that NEAT1/Neat1 expression is significantly elevated in both patients with heart failure and in a mouse model of TAC-induced heart failure." (PMID 34980170, 2022). "Therefore, NEAT1 might also be a potential novel biomarker for heart failure." (PMID 34980170, 2022). "Among these, lncRNAs, such as Fetal lethal non-coding developmental regulatory RNA (FENDRR), ZNFX1 antisense RNA 1 (ZFAS1), and nuclear paraspeckle assembly transcript 1 (NEAT1) have been found to participate in a variety of pathophysiological processes, including AMI and heart failure (HF)." (PMID 40948766, 2025). "Interestingly, we found two lncRNAs (NEAT1 and AC005154.6) were all crucial in each feature, indicating that the two lncRNA might function as a crucial regulators in the pathology processes of heart failure." (PMID 30019841, 2018).
lymphoma (7 papers, 2017 to 2023). A malignant (clonal) proliferation of B- lymphocytes or T- lymphocytes which involves the lymph nodes, bone marrow and/or extranodal sites. "In summary, NEAT1 tumour mutations consistently increase cell fitness in vitro and in vivo, in a range of genetic backgrounds, and are associated with poor prognosis in lymphoid cancer patients." (PMID 37291246, 2023). "According to our results, hsa-miR-150-5p, hsa-miR-335-5p, MALAT1 and NEAT1 were differentially expressed in patients with high grade lymphomas when compared to low grade lymphoma patients, indicating their involvement in the pathogenesis and prognosis of NHL." (PMID 35008626, 2021). "The plasma levels of MALAT1 and NEAT1 were higher in patients with high grade lymphoma compared to low grade lymphoma (p = 0.035 and p = 0.018, respectively)." (PMID 35008626, 2021). "Further analysis revealed that GAS5, DLEU2, and nuclear paraspeckle assembly transcript 1 (NEAT1) were previously identified in lymphoma." (PMID 33519750, 2020). "Indeed, in lymphoid cancer patients from the PCAWG cohort, NEAT1 mutations correlate with significantly worse prognosis." (PMID 37291246, 2023).
chronic myeloid leukemia (6 papers, 2019 to 2024). "Meanwhile, METTL3-modified lncRNA NEAT1 inhibits the progression of chronic myeloid leukemia (CML) by downregulating miR-766-5p targeting cyclin-dependent kinase inhibitor 1A (CDKN1A)." (PMID 38351139, 2024). "MYC has been shown to bind to the promoter of NEAT1, and suppression of NEAT1 expression regulates cell apoptosis in chronic myeloid leukaemia (CML)." (PMID 32206038, 2020). "NEAT1 is regulated by c-myc and inhibits imatinib-induced apoptosis of chronic myeloid leukemia cells." (PMID 31243262, 2019). "In addition, MYC can bind to NEAT1 and inhibit its expression to regulate cell apoptosis in chronic myeloid leukaemia (CML)." (PMID 32206038, 2020).
cognitive decline (6 papers, 2020 to 2024). "It is invaluable to understand the function of lncRNA NEAT1 in regulating mitophagy which protects brain from cognitive decline." (PMID 32140098, 2020). "upregulated NEAT1 can give rise to the amyloid accumulation and cognitive decline in AD." (PMID 37510227, 2023).
diffuse large B-cell lymphoma (6 papers, 2020 to 2024). "However, the underlying mechanism of lncRNA NEAT1 in diffuse large B-cell lymphoma (DLBCL) progression is unclear." (PMID 32206038, 2020). "c-Myc regulates the lncRNA NEAT1 to promote B-cell proliferation and lymphomagenesis in diffuse large B-cell lymphomas." (PMID 34490239, 2021). "The tumor driver NEAT1 acts as a ceRNA to regulate the miR-34b-5p-GLI1 axis, further affecting the proliferation of diffuse large B-cell lymphoma." (PMID 33820555, 2021). "NEAT-1 promotes lymphomagenesis and B-cell proliferation through a MYC-regulated mechanism in diffused large B-cell lymphoma, and it has been reported to be overexpressed in patients with diffused large B-cell lymphoma." (PMID 39184920, 2024). "For example, it was found that MYC-regulated NEAT1 promoted diffuse large B-cell lymphoma (DLBCL) proliferation via the miR-34b-5p-GLI1 pathway, which could provide a novel therapeutic target for DLBCL." (PMID 35127729, 2021).
gastric adenocarcinoma (6 papers, 2016 to 2025). "As matter of fact, during tumorigenesis NEAT1 levels are increased, and high levels of NEAT1 were associated with worse prognosis in gastric adenocarcinoma and laryngeal SCC118,119." (PMID 32194993, 2020). "Here, we report a novel finding about the abnormal NEAT1 lncRNA expression in gastric adenocarcinomas (GACs)." (PMID 26911892, 2016). "The aim of this study was to examine the abnormalities of NEAT1 (nuclear paraspeckle assembly transcript 1, also known as MENε/β) in gastric adenocarcinomas (GACs)." (PMID 26911892, 2016).
inflammatory bowel disease (6 papers, 2020 to 2025). A spectrum of small and large bowel inflammatory diseases of unknown etiology. "NEAT1 was selected from the LncRNADisease v3.0 database for its reported association with inflammatory bowel disease." (PMID 41465348, 2025). "For instance, Neat1 expression is significantly upregulated in the serum of mice and humans with inflammatory bowel disease (IBD)." (PMID 40362651, 2025). "According to a report on inflammatory bowel disease, increased NEAT1 expression is involved in inflammatory responses by controlling exosome‐mediated macrophage polarity." (PMID 35266286, 2022). "Further, NEAT1 is overexpressed in inflammatory bowel disease patients and participates in the inflammatory response by regulating the intestinal epithelial barrier and exosome-mediated polarization of macrophages." (PMID 32185228, 2020). "Additionally, blocking NEAT1 expression may treat inflammatory bowel disease by suppressing inflammatory progression." (PMID 32089649, 2020). "LncRNAs NEAT1 and PTPRE-AS1 are involved in the occurrence and development of inflammatory bowel disease." (PMID 35011565, 2021).
kidney cancer (6 papers, 2019 to 2025). Primary or metastatic malignant neoplasm involving the kidney. "Similarly, for a disease node with a lower degree, such as kidney cancer, potential association with the lncRNA NEAT1 is identified." (PMID 39797570, 2025). "Research conducted by Liu has demonstrated that NEAT1 promotes the proliferation and migration of kidney cancer cells." (PMID 39797570, 2025). "For instance, METTL14 has been demonstrated to restrain the growth and metastasis of kidney cancer by reducing the expression of lncRNA NEAT1." (PMID 38528591, 2024). "RT-qPCR analysis showed that NEAT1 was highly expressed in kidney cancer cell lines compared to that in HK-2, with more significant differences in 786-O and ACHN cell lines." (PMID 35425712, 2022). "In BAP1-deficient ccRCC, NEAT1 competitively binds to miR-10a-5p, indirectly upregulating SERPINE1 expression to promote kidney cancer cell proliferation." (PMID 35425712, 2022). "Nuclear enriched abundant transcript 1 (NEAT1) expression was significantly increased in kidney cancer cell lines." (PMID 35425712, 2022). "Therefore, NEAT1 serves as a sponge for miR-10a-5p and inhibit its function in kidney cancer cells." (PMID 35425712, 2022).